NKAPL (NFKB activating protein like)
Description:
Transcriptional repressor of Notch-mediated signaling. Required for spermatogenesis.
Synonyms: C6orf194; bA424I5.1
Tractability: PROTAC: ubiquitination databases record sites on it.
Gene: Protein-coding gene on chromosome 6 (28,259,297 to 28,260,958, forward strand). Ensembl gene ENSG00000189134.
Subcellular location: Nucleus
Subcellular location (Human Protein Atlas): Golgi apparatus; Nucleoplasm
Gene Ontology:
Molecular function: protein binding; chromatin binding
Cellular component: nucleus
Genetic constraint (gnomAD): Loss-of-function variants: 7 observed, 16.19 expected, observed/expected ratio (o/e) 0.43, 90% interval 0.25 to 0.81. The upper end of that interval is the gene's LOEUF score, 0.81, which puts it in group 3 of 6, group 1 being the genes least tolerant of losing a copy. Missense variants: 466 observed, 519.48 expected, observed/expected ratio (o/e) 0.9, 90% interval 0.83 to 0.97. Synonymous variants: 192 observed, 190.77 expected, observed/expected ratio (o/e) 1.01, 90% interval 0.89 to 1.13.
Homologues: Orthologues: chimpanzee NKAPL (97% identical), macaque NKAPL (89% identical), pig NKAPL (76% identical), mouse Nkapl (67% identical), rat Nkapl (66% identical), guinea pig NKAPL (62% identical), tropical clawed frog nkap (54% identical), zebrafish nkap (52% identical), Drosophila melanogaster CG6066 (40% identical), Caenorhabditis elegans let-504 (36% identical). Paralogues in human: NKAP (65% identical).
Diseases named in the same sentence as NKAPL in open-access papers:
NKAPL is named in the same sentence as 17 diseases in open-access papers, as found by Europe PMC text mining. Sharing a sentence is not in itself a finding about the gene and the disease. The quoted sentences say what the papers report.
schizophrenia (4 papers, 2013 to 2022). A major psychotic disorder characterized by abnormalities in the perception or expression of reality. "The SNP rs1635 of the NKAPL gene encodes a threonine-to-glutamine substitution at amino acid 152 in exon 1 of NKAPL, and was previously shown to associate with schizophrenia in separate Han Chinese populations." (PMID 28095483, 2017). "Therefore, we conducted this study to further explore the association between NKAPL variant rs1635 and cognitive function across different domains in patients with schizophrenia." (PMID 35801084, 2022). "Moreover, according to the HapMap database (release #24, CHB), rs1635 is in linkage disequilibrium (LD) with another NKAPL SNP rs12000 which is a missense mutation linked to Schizophrenia." (PMID 28095483, 2017). "The variant rs1635 (nucleotide sequence: c.455C>A; amino acid sequence: T152N) located on the (NFKB activating protein like) NKAPL gene confers risk for schizophrenia and might play a role in the neurodevelopmental process, which is particularly relevant to cognitive function." (PMID 35801084, 2022). "The variant decreases the phosphorylation of NKAPL and decreases its transcription in the peripheral blood, which provides new insights for elucidation of the roles and mechanisms of this risk variant in schizophrenia and helps explore prevention for cognition impairment in EOS." (PMID 35801084, 2022). "Demographic and clinical characteristics of patients with early-onset schizophrenia in two groups of NKAPL rs1635 genotype." (PMID 35801084, 2022). "We speculate that genetic variation in NKAPL gene causes a disbalance in CD8+ TEM and TDN production and might be one of the reasons for the higher prevalence of schizophrenia in populations with Asian background when compared with Europeans." (PMID 31228201, 2019). "As EOS become symptomatic during a critical period for major changes in the neural systems, and genetic risk factors play a more salient role in EOS, the regulation of neuronal development by NKAPL may be part of the factors affecting cognitive function in early-onset schizophrenia." (PMID 35801084, 2022). "Further study on the biological function of SNP rs1635 or NKAPL gene may provide a new understanding of the mechanism of cognitive impairment in patients with schizophrenia, thereby providing an attractive treatment method targeting the phosphorylation of NKAPL." (PMID 35801084, 2022). "Additionally, our earlier two-stage GWAS also found that three single-nucleotide polymorphisms (SNPs; i.e., rs1233710 in ZKSCAN4, rs1635 in NKAPL, and rs2142731 in PGBD1) within this locus had a strong association with schizophrenia in a Chinese Han population." (PMID 23437227, 2013).
liver cancer (2 papers, 2024 to 2025). An epithelial or non-epithelial malignant neoplasm that arises from the liver. "In the context of liver cancer, the high methylation level and low expression of NKAPL are associated with poor prognosis." (PMID 38495498, 2024). "Other research found low NKAPL levels were linked with worse outcomes in liver cancer." (PMID 38495498, 2024). "The NKAPL promoter is hypermethylated in liver cancer, which suppresses the expression of NKAPL and indicates a poor prognosis." (PMID 40605974, 2025). "Conversely, in liver cancer, promoter hypermethylation-induced low expression of NKAPL results in a poor prognosis." (PMID 40605974, 2025).
breast carcinoma (1 paper, 2022). "Oncogenic genes like FAM83D, CTDSP1, and SAPCD2 were downregulated in all three cells, and tumor suppressor genes (TSGs) like ZNF292, ANKRD12, NKAPL, and CCL21 were upregulated in all three breast cancer cells upon curcumin treatment." (PMID 34981672, 2022).
Cognitive impairment (1 paper, 2022). Abnormal cognition is characterized by deficits in thinking, reasoning, or remembering. "CONCLUSION: The present study found that NKAPL rs1635 was associated with cognitive impairments and peripheral blood mRNA expression level in EOS patients." (PMID 35801084, 2022). "However, it is unclear whether NKAPL is related to cognitive impairments." (PMID 35801084, 2022).
depression (1 paper, 2023). "Notably, TCF4, NKAPL, ZKSCAN3, ZSCAN16, ZSCAN31 have been associated with depression in previous GWASs." (PMID 36750733, 2023).
insomnia (1 paper, 2022). A sleep disorder characterized by difficulty in falling asleep and/or remaining asleep. "Tumor suppressor genes, CMTM7, NKAPL and ATM (encoding ATM checkpoint kinase) may allude to aberrant DNA damage responses contributing to insomnia, and indeed, there are several reports of links between DNA damage and sleep in the literature." (PMID 35711912, 2022).
lung adenocarcinoma (1 paper, 2025). A carcinoma that arises from the lung and is characterized by the presence of malignant glandular epithelial cells. "According to the analysis of the pan-cancer NKAPL methylation status, NKAPL was highly methylated in various tumors, including NSCLC (lung adenocarcinoma and lung squamous cell carcinoma)." (PMID 40605974, 2025).
male infertility (1 paper, 2015). The inability of the male to effect fertilization of an ovum after a specified period of unprotected intercourse. "Therefore, the possibility that genetic mutations or polymorphisms in human NKAPL are associated with human male infertility is being examined." (PMID 25875095, 2015).
rheumatoid arthritis (1 paper, 2025). A chronic, systemic autoimmune disorder characterized by inflammation in the synovial membranes and articular surfaces. "Large-scale data analysis has revealed that the NKAPL gene is a susceptibility locus for rheumatoid arthritis." (PMID 40605974, 2025).
serous ovarian cancer (1 paper, 2025). "Furthermore, abnormal methylation of NKAPL has been shown to be associated with increased acquired platinum resistance in high-grade serous ovarian cancer." (PMID 40605974, 2025).
triple-negative breast carcinoma (1 paper, 2025). An invasive breast carcinoma which is negative for expression of estrogen receptor (ER), progesterone receptor (PR), and human epidermal growth factor receptor 2 (HER2). "Notably, NKAPL methylation and expression levels serve as crucial markers for the diagnosis and prognosis prediction of triple-negative breast cancer patients." (PMID 40605974, 2025). "Moreover, previous studies have suggested that NKAPL may serve as a prognostic biomarker in triple-negative breast cancer." (PMID 40605974, 2025).
cancer (5 papers, 2017 to 2025). A tumor composed of atypical neoplastic, often pleomorphic cells that invade other tissues. "Previous studies have demonstrated that the NF-kappa-B activating protein like (NKAPL) is positively correlated with prognosis in several types of cancers." (PMID 40605974, 2025). "First, the expression levels of NKAPL in various cancers were detected, the results of which indicated that NKAPL was down-regulated in various human cancer types." (PMID 40605974, 2025). "Thanks to the second model, it was noticed that in the normal cell lines (MCF-10A) around the NKAPL gene, several times more interactions can be identified compared to the cancer cell line (MCF-7), with a similarly higher level of DNA methylation in cancer." (PMID 40724805, 2025). "In contrast, lower expression of the downregulated genes (such as SCARA5, MYOM1, NKAPL, PEG3, USP2, SLC5A7 and HMGCLL1) in various cancers is associated with poor clinical outcomes in cancer." (PMID 28427185, 2017). "Accordingly, NKAPL was down-regulated in cancer samples, which could be explained by hyper-methylation of the five DMSs." (PMID 40724805, 2025). "Additionally, both 3D models are showing the loci with differential DNA methylation around the NKAPL gene, reflecting higher DNA methylation in cancer." (PMID 40724805, 2025). "Finally, a recent analysis based on human cancer transcriptome data demonstrated that NKAPL is a consistently downregulated gene across various cancers." (PMID 38059855, 2024). "Emerging evidence suggests a link between altered NKAP/NKAPL activity and cancer development." (PMID 38059855, 2024). "Another gene called NKAPL shows decreased activity in the cancers we studied." (PMID 38495498, 2024). "Consequently, we conducted a pan-cancer analysis of gene promoter methylation and observed significant associations between several genes, including ZNF323, ZSCAN23, SCAND3, PRSS16, ZNF391, NKAPL, and ZNF311, and promoter methylation." (PMID 38495498, 2024). "It was confirmed that the identified cohesin-mediated loops (significant interactions) connecting two distant genomic fragments (anchors) surrounding the NKAPL gene were stronger and higher in number in hTERT-HME1 (normal) than the MCF-7 (cancer)." (PMID 40724805, 2025). "We identified consistently upregulated genes (such as E2F1, EZH2, FOXM1, MYBL2, PLK1, TTK, AURKA/B and BUB1) and consistently downregulated genes (such as SCARA5, MYOM1, NKAPL, PEG3, USP2, SLC5A7 and HMGCLL1) across various cancers." (PMID 28427185, 2017). "More importantly, we found a number of genes commonly dysregulated in various cancers such as PLP1, MYOM1, NKAPL and USP2 which were investigated in few cancer related studies, and thus represent our novel findings." (PMID 28427185, 2017). "NKAPL (NKAP-like) is a cell-specific transcriptional suppressor in Notch signaling, and its reduced expression in cancer has been indicated by several articles, just as the relationship between DMS hyper-methylation and the demonstrated change in NKAPL expression." (PMID 40724805, 2025). "For example, patients with higher expression levels of NKAPL have better OS prognoses than those with lower expression levels of NKAPL in four cancer types (ACC, KIRP, LGG, and PAAD), and better DFS prognoses in three cancer types (ACC, KIRP, and THYM) (log-rank test, unadjusted P-value < 0.05)." (PMID 28427185, 2017). "However, few studies have shown that PLP1, MYOM1, NKAPL, and USP2 were consistently downregulated in various cancers." (PMID 28427185, 2017).
tumor (2 papers, 2025). "The in vivo experiments indicated that the overexpression of NKAPL substantially inhibited tumor growth and metastasis in the metastatic mouse models." (PMID 40605974, 2025). "As shown in the in vivo fluorescence imaging results, the overexpression of NKAPL significantly reduced the fluorescence intensity of metastatic cells in the lung, which was per the results of tumor hematoxylin-eosin staining." (PMID 40605974, 2025). "Collectively, the data presented above illustrate the role of NKAPL as a newly verified tumor suppressor in NSCLC." (PMID 40605974, 2025). "We investigated the effects of NKAPL on NSCLC in vivo via a xenograft tumor model." (PMID 40605974, 2025). "The proposed regulatory model suggests that hypermethylation at five cytosine loci within the NKAPL promoter may obstruct NRF1 binding, either by diminishing its affinity or through MBD protein binding, resulting in its down-expression in tumor samples." (PMID 40724805, 2025). "The tumor volumes of the xenografts constructed with the NKAPL-overexpressing NSCLC cells were significantly smaller than the volume of those constructed with the control cells (vector), and the NKAPL-overexpressing xenograft tumors weighed less than did those in the vector group." (PMID 40605974, 2025).
NKAPL also shares sentences with these, for which no sentence is quoted: bladder cancer (1 paper); chronic myeloid leukemia (1); COVID-19 (1); lung squamous cell carcinoma (1).